TRIB3 (tribbles pseudokinase 3)
Diseases named in the same sentence as TRIB3 in open-access papers (continued):
Sharing a sentence is not in itself a finding about the gene and the disease.
ovarian carcinoma (continued). "This study revealed that the EMT process was inhibited following inhibition of TRIB3 expression in ovarian cancer cell lines." (PMID 32874132, 2020). "Simultaneously, multiple bioinformatics databases were used to objectively analyze the functions and mechanisms of action of TRIB3 in ovarian cancer progression." (PMID 32874132, 2020). "The TISIDB database was used to analyze the expression of TRIB3 in the molecular sub-types of ovarian cancer." (PMID 32874132, 2020). "Consistent results were obtained during the analysis of TRIB3 expression in 426 cases of ovarian cancer and 88 individuals with normal ovarian tissue, in the GEPAI database." (PMID 32874132, 2020). "The analysis revealed that the TRIB3 protein and mRNA were both higher in ovarian cancer tissues than benign and normal ovarian tissues (P < 0.05)." (PMID 32874132, 2020). "In ovarian cancer, TRIB3 downregulation inhibits progression via the MEK/ERK signaling pathway." (PMID 34359681, 2021). "In the present study, through immunohistochemical experiments, western blot and qRT-PCR, we identified that TRIB3 was highly expressed in ovarian cancer in protein and mRNA level, which was confirmed by expression analysis studies in the Oncomine and GEPAI databases." (PMID 32874132, 2020). "This was the first study to confirm that TRIB3 down-regulation may activate the MEK/ERK signaling pathway in ovarian cancer cells." (PMID 32874132, 2020). "In this study, following inhibition of TRIB3 expression in the ovarian cancer cell lines OVCAR3 and ES-2, it was found that the proliferation, migration, and invasion, of the ovarian cancer cells decreased, apoptosis increased, and cell cycle arrest occurred at the G0/G1 phase." (PMID 32874132, 2020). "Mechanistically, TRIB3 may promote the malignant behavior of ovarian cancer by activating the MEK/ERK signaling pathway." (PMID 32874132, 2020). "However, when compared to the benign group (35.7%) and normal ovarian tissue groups (23.1%), the positive expression level of TRIB3 was significantly higher in the ovarian cancer group (75.7%) (P < 0.01)." (PMID 32874132, 2020). "This shows that TRIB3 expression has a cancer-promoting role in ovarian cancer." (PMID 32874132, 2020). "Similarly, in lung, breast, and ovarian cancers, high TRIB3 expression promotes tumor malignancy." (PMID 35726370, 2022). "However, the expression and function of TRIB3 in ovarian cancer is unknown." (PMID 32874132, 2020). "In the previous study, we used gene chip technology to show that the expression of TRIB3, over-expressed by human epididymis protein 4 (HE4), was significantly up-regulated in ovarian cancer cells." (PMID 32874132, 2020). "It was further proved that TRIB3 over-expression promotes cell proliferation, cell cycle, invasion, migration and EMT of ovarian cancer cells, while inhibiting apoptosis." (PMID 32874132, 2020). "However, the expression of TRIB3 and its effect on the malignant biological behavior of ovarian cancer has not been reported." (PMID 32874132, 2020).
prostate carcinoma (6 papers, 2014 to 2025). A carcinoma that arises from epithelial cells of the prostate gland. "In conclusion, these findings suggested that TRIB3 inhibition by palbociclib could increase the susceptibility of prostate cancer cells to ferroptosis." (PMID 39362848, 2024). "Interestingly, the overexpression of TRIB3 appeared to counteract the palbociclib-induced G1 phase arrest and the associated decline in colony formation in prostate cancer cells." (PMID 39362848, 2024). "Specifically, TRIB3 knockdown augmented the response of prostate cancer cells to ferroptosis inducers, whereas, TRIB3 overexpression rescued prostate cancer cells from palbociclib-induced ferroptosis." (PMID 39362848, 2024). "In the current study, we discovered that palbociclib promotes ferroptosis susceptibility of prostate cancer LNCaP and PC3 cells, and TRIB3 was significant inhibited upon palbociclib treatment." (PMID 39362848, 2024). "Collectively, these findings suggest that palbociclib induces ferroptosis in prostate cancer cells by inhibiting the expression of TRIB3, thereby reducing SLC7A11 expression via SOX2." (PMID 39362848, 2024). "To explore the molecular mechanisms downstream TRIB3 that mediates ferroptosis induced by palbociclib in prostate cancer cells, we examined the expression of ferroptosis-related genes upon palbociclib treatment." (PMID 39362848, 2024). "Conversely, TRIB3 overexpression conferred resistance to erastin in prostate cancer cells, highlighting a potential therapeutic target." (PMID 39362848, 2024). "In our research, we observed a pronounced overexpression of TRIB3 in prostate cancer tissues, which significantly promotes cell proliferation and colony formation." (PMID 39362848, 2024). "In this study, we reported in prostate cancer that palbociclib is a potent sensitizer of ferroptosis, which is worked out by downregulating the expression of TRIB3, a gene highly expressed in prostate cancer." (PMID 39362848, 2024). "Together, these results suggested that TRIB3 is a pivotal target of palbociclib, which was involved in cell cycle control and cell proliferation in prostate cancer cells." (PMID 39362848, 2024). "Consistently, colony formation was significantly compromised upon TRIB3 knockdown in prostate cancer cells, suggesting an essential role of TRIB3 in prostate cancer." (PMID 39362848, 2024). "Conversely, it is supposed that TRIB3 overexpression mitigated the toxicity of ferroptosis inducers on prostate cancer cells, especially reducing erastin’s cytotoxic effect." (PMID 39362848, 2024). "Exposure to GA increased the levels of TRIB3 in breast and prostate cancer cell lines, as did exposure to the 2-D08 SUMO inhibitor." (PMID 31578236, 2019). "To determine whether TRIB3 mediates the inhibitory effects of palbociclib on the growth of prostate cancer cells, we ectopically expressed TRIB3 in LNCaP and PC3 cells." (PMID 39362848, 2024). "Moreover, TRIB3 inhibition not only promotes cell cycle arrest but also ferroptosis in prostate cancer cells, whereas, overexpression of TRIB3 counteracts the ferroptotic response to palbociclib." (PMID 39362848, 2024). "Notably, TRIB3 levels were found to be elevated in prostate cancer patients (P < 0.05), to explored the role of TRIB3 in cell cycle control of prostate cancer cells, two stable TRIB3 knockdown (KD) cell lines were generated for both LNCaP and PC3 cells using short hairpin RNA (shRNA)." (PMID 39362848, 2024). "Therefore, under the treatment with etomoxir, TRIB3 could act as a nutrient sensor and prevent cells from undergoing apoptosis as described in prostate cancer cells." (PMID 24834131, 2014). "Our study found that palbociclib affects the cellular iron and GSH content through TRIB3/SOX2/SLC7A11 signaling axis, disrupting the cellular redox balance and promoting ferroptosis in prostate cancer cells." (PMID 39362848, 2024).
prostate carcinoma (continued). "Together, these results uncover an essential role of TRIB3/SOX2/SLC7A11 axis in palbociclib-induced ferroptosis, suggesting palbociclib a promising targeted therapy in combine with ferroptosis induction for the treatment of prostate cancer." (PMID 39362848, 2024).
atherosclerosis (5 papers, 2013 to 2025). A disease characterized by the build-up of fatty material and calcium deposition in the arterial wall resulting in partial or complete occlusion of the arterial lumen. "Using a mouse model of atherosclerosis, loss of TRIB3 resulted in increased macrophage numbers in atherosclerotic plaques and increased plaque stability features of thicker fibrous caps and an increase in collagen." (PMID 36158793, 2022). "Loss of TRIB3 in a full body knockout mouse model of atherosclerosis results in reduced atherosclerotic burden via increased collagen and fibrous cap thickness and increased macrophage plaque content." (PMID 36158793, 2022). "Since we found that TRIB3 was upregulated in vulnerable and unstable regions of human plaques we used a Trib3KO mouse model of atherosclerosis to assess the consequences of Trib3-deficiency in atherosclerosis development and in fibrous cap formation." (PMID 36158793, 2022). "Here we have shown that genetic deletion of Trib3 mediates changes in body weight supporting effects for atherosclerosis development in vivo." (PMID 36158793, 2022). "Notably, TRIB3 is expressed by several cells and therefore holo-TRIB3 deficiency could have pleiotropic effects on multiple cell types, including vascular endothelial cells, adipocytes, and pancreatic β cells, all of which could influence the progression of atherosclerosis." (PMID 41186004, 2025). "Finally, using a preclinical mouse model of advanced atherosclerosis, we show that targeting TRIB3 in atheroma could be an attractive therapeutic strategy to improve lesional macrophage efferocytosis efficiency, decrease plaque necrosis, and promote atherosclerotic plaque stabilization." (PMID 41186004, 2025).
breast tumors (5 papers, 2011 to 2024). "TRIB3 mRNA expression was measured in breast tumor tissue from 247 patients and correlated with clinicopathological parameters and clinical outcome." (PMID 21864376, 2011). "Therefore, we opted to analyze TRIB3 protein levels in a Tissue microarray that was generated from a prospective cohort of 291 patients classified as luminal (hormone-dependent) breast tumors." (PMID 34771470, 2021). "Indeed, the TRIB3/AKT1 interaction was abrogated in MMTV-PyMT MEC-derived breast tumors and PDX breast tumors." (PMID 31844113, 2019). "Combined with the observation that TRIB3 is mostly expressed in the therapy resistant hypoxic areas of breast tumors this indicates that the prognostic role of TRIB3 could indeed be a consequence of therapy resistance." (PMID 21864376, 2011). "It has been demonstrated that Pep2–Ae binding to TRIB3 enhanced the activity of AKT1 in MEC- and PDX-derived breast tumors." (PMID 38731938, 2024).
clear cell renal cell carcinoma (5 papers, 2021 to 2024). "Additionally, overexpression of VSX1 has been shown to increase the activity of TMEM44, FKBP10, and TRIB3, and enhance the growth of renal clear cell carcinoma." (PMID 37561335, 2024).
leukemia (5 papers, 2020 to 2022). A malignant (clonal) hematologic disorder, involving hematopoietic stem cells and characterized by the presence of primitive or atypical myeloid or lymphoid cells in the bone marrow and the blood. "In a study involving leukemia, researchers confirmed that TRIB3 protein could bind to the WR domain of TWIST1 and contribute to its stability, by inhibiting its ubiquitination." (PMID 32874132, 2020). "Leukemia cells from most APL patients showed reduced PPARγ protein expression and enhanced resistin and TRIB3 protein levels compared with those in leukemia cells from non-APL patients." (PMID 32929351, 2020).
metabolic syndrome (5 papers, 2012 to 2025). A cluster of metabolic risk factors for CARDIOVASCULAR DISEASES and TYPE 2 DIABETES MELLITUS. "In addition, we provide evidence that a common SNP in TRIB3 (Q84R) in humans is associated with impairment in macrophage efferocytosis efficiency at baseline, which is further exacerbated under conditions of atherogenic dyslipidemia." (PMID 41186004, 2025). "In summary, our study not only reveals a critical role of the PML-RARα/PPARγ/TRIB3 axis in dyslipidemia for patients with APL but also confers a rationale for the combination of ATRA/arsenic with the PPAR activator for the treatment of patients with APL." (PMID 32929351, 2020). "Indeed, the PPAR activator not only enhanced the anti-APL effects of arsenic/ATRA by suppressing TRIB3 expression but also reduced therapy-induced dyslipidemia in APL patients." (PMID 32929351, 2020). "In this study, we verified the hypothesis that the metabolic stress sensor TRIB3 collaborates with the oncoprotein PML-RARα to inhibit PPARγ activity and subsequently cause dyslipidemia in newly diagnosed APL patients." (PMID 32929351, 2020). "Therefore, we herein hypothesize that the increased TRIB3 expression functions together with PML-RARα to participate in the regulation of dyslipidemia in patients with APL." (PMID 32929351, 2020). "The TRIB3 expression that was increased by ATRA/As2O3 treatment further impeded PPARγ activity by forming the heterotrimer of TRIB3, PML-RARα and PPARγ, contributing to dyslipidemia in APL patients undergoing anti-APL therapy." (PMID 32929351, 2020). "The elevated TRIB3 expression in response to arsenic/ATRA therapy suppressed PPARγ activity by disrupting the PPARγ/RXR dimer, which resulted in dyslipidemia in APL patients undergoing therapy." (PMID 32929351, 2020). "Interestingly, we found that PPAR agonists can reduce arsenic/ATRA-induced dyslipidemia in APL patients and decrease TRIB3 expression in APL cells." (PMID 32929351, 2020). "Importantly, ATRA treatment induced increased serum TG levels in Pml-Rarα transgenic mice but did not elevate TG levels in Trib3-knockout Pml-Rarα transgenic mice (PR-T3KO), indicating that TRIB3 is involved in the regulation of anti-APL-therapy-induced dyslipidemia in individuals with APL." (PMID 32929351, 2020).
non-small cell lung carcinoma (5 papers, 2018 to 2022). A group of at least three distinct histological types of lung cancer, including non-small cell squamous cell carcinoma, adenocarcinoma, and large cell carcinoma. "It has been demonstrated that Sal suppresses AKT1 activity through ATF4- DDIT3/CHOP- TRIB3- AKT1 axis in human non-small cell lung cancer (NSCLC) cells after activation of ER stress response, resulting in mTOR inhibition and autophagy consequently." (PMID 29433536, 2018). "Finally, evidence in the literature for gastric, liver, colorectal, renal cell, and non-small-cell lung carcinoma suggest increased TRIB3 protein level in the tumor tissue compared to the adjacent non-tumor tissue." (PMID 33920424, 2021).
renal carcinoma (5 papers, 2020 to 2023). A carcinoma arising from the epithelium of the renal parenchyma or the renal pelvis. "In renal cancer, TRIB3 is overexpressed compared to normal tissue and is associated with tumor progression and poor prognosis." (PMID 34580365, 2021). "Hong et al24 found that TRIB3 plays a vital role in the biological processes of migration and invasion of renal cancer cells by regulating the MAPK pathway." (PMID 32160655, 2020). "Notably, TRIB3 is expressed in CD4T/CD8T cells and monocyte-macrophages across almost all datasets, consistent with the findings from single-cell data on renal cancer." (PMID 38235126, 2023).
acute myeloid leukemia (4 papers, 2016 to 2022). Acute myeloid leukemia (AML) is a group of neoplasms arising from precursor cells committed to the myeloid cell-line differentiation. "Tribbles homolog 3 (TRIB3) has been identified as an oncoprotein in acute myeloid leukemia via the inhibition of apoptosis and autophagy." (PMID 35954274, 2022).
bladder cancer (4 papers, 2018 to 2023). "Expression levels of TRIB3 increased with increased stage and grade, suggesting that TRIB3 promotes the progression of bladder cancer and increases the risk of invasion and deterioration of bladder cancer." (PMID 33841505, 2021). "We downloaded transcriptome data and clinical data of bladder cancer from associated databases and extracted the expression matrix of TRIB3 for multiple bioinformatics analysis." (PMID 33841505, 2021). "Although more clinical samples and more in-depth experiments are needed to explore the mechanism of TRIB3 in the future, our results suggest that TRIB3 is a potential prognostic marker and therapeutic target in bladder cancer." (PMID 33841505, 2021). "One of the main findings of this study was that TRIB3 is a robust prognostic biomarker of bladder cancer." (PMID 33841505, 2021). "After inhibiting the expression of TRIB3 in bladder cancer cells, we found that the proliferation and migration of bladder cancer cells decreased." (PMID 33841505, 2021). "Because of the high expression of TRIB3 in bladder cancer and poor outcome, we knocked down TRIB3 in bladder cancer cells and conducted functional experiments further to explore the function of TRIB3." (PMID 33841505, 2021). "In the present study, we used several bladder cancer cohorts and online databases to explore the prognostic potential of TRIB3 and to explore the mechanisms of TRIB3 in bladder cancer cells through functional experiments in vitro." (PMID 33841505, 2021). "Using web tool “UALCAN” to query the data of TRIB3 expression in bladder cancer tissues and normal tissues, we found that TRIB3 was highly expressed in tumor tissues (p < 0.001)." (PMID 33841505, 2021). "The analysis results showed that TRIB3 was relatively highly expressed in 35 of the 40 pairs of bladder cancer tissue samples." (PMID 33841505, 2021). "We conclude from these results that TRIB3 is a potential oncogene and a potential therapeutic target for bladder cancer." (PMID 33841505, 2021). "The Transwell analysis showed that si-TRIB3 bladder cancer cells’ migration ability was significantly lower (p < 0.05)." (PMID 33841505, 2021). "In the present study, we combined computational biology methods and experimental verification methods to identify and characterize the role of pseudokinase-TRIB3 in poor outcomes and malignant progression of bladder cancer." (PMID 33841505, 2021). "Then flow cytometry verified that the proportion of the bladder cancer cells transfected by TRIB3-siRNA in the G0/G1 phase was significantly increased (p < 0.05), as compared to the cells transfected by TRIB3-NC." (PMID 33841505, 2021). "In our further study, we discovered that FOXD2-AS1 formed a positive feedback loop with Akt and E2F1, which served as a newly identified reason for consistently activated TRIB3/Akt pathway in bladder cancer." (PMID 29445134, 2018). "Next, siRNAs targeted to the two hnRNPs were transfected into bladder cancer cells, and expression of TRIB3 was measured by western blotting." (PMID 29445134, 2018). "Taken together, our observations strongly suggest that TRIB3 might have a pro-oncogenic role in bladder cancer." (PMID 33841505, 2021). "Moreover, to assess the clinical significance of TRIB3 expressions in bladder cancer, the clinical characteristics between TRIB3 and bladder cancer were evaluated in tissues." (PMID 33841505, 2021). "TRIB3 successfully predicted outcome in patients with bladder cancer in two meta-cohorts." (PMID 33841505, 2021). "The clinical significance of TRIB3 expressions in bladder cancer." (PMID 33841505, 2021). "We confirmed high expression levels of TRIB3 mRNA in bladder cancer cells using qRT-PCR." (PMID 33841505, 2021). "RT-PCR detected the expression of TRIB3 in bladder cancer cells." (PMID 33841505, 2021). "This experiment suggests that expression of TRIB3 plays a tumor-promoting role in bladder cancer." (PMID 33841505, 2021).